COL15A1 (collagen type XV alpha 1 chain)
Diseases named in the same sentence as COL15A1 in open-access papers (continued):
Sharing a sentence is not in itself a finding about the gene and the disease.
COL15A1 also shares sentences with these, for which no sentence is quoted: glioblastoma (2 papers); lung disease (2); malignant neoplasm of the thyroid gland (2); primary open angle glaucoma (2); adrenocortical carcinoma (1); Arthritis (1); bladder urothelial carcinoma (1); cervical squamous cell carcinoma (1); cholangiocarcinoma (1); clear cell renal cell carcinoma (1); coeliac disease (1); colon adenocarcinoma (1); colorectal cancer (1); connective tissue diseases (1); Dupuytren Contracture (1); endocervical adenocarcinoma (1); esophageal carcinoma (1); heart failure (1); hepatoblastoma (1); hyperthyroidism thyrotoxicosis (1); infection (1); keratoconus (1); Lewis lung carcinoma (1); lymphoid neoplasm (1); melanoma (1); pancreatic adenocarcinoma (1); pancreatic carcinoma (1); pterygium (1); rectum adenocarcinoma (1); renal fibrosis (1).
A further 6 diseases each share a sentence with COL15A1 in 1 paper.